BRCA1 (BRCA1 DNA repair associated)
Diseases named in the same sentence as BRCA1 in open-access papers (continued):
Sharing a sentence is not in itself a finding about the gene and the disease.
breast tumors (501 papers, 2001 to 2026). "In both clinical databases, ELF3 expression is significantly higher in BRCA1-associated breast tumors than in non-BRCA1-associated breast tumors." (PMID 41498327, 2026). "This study reveals distinct patterns in the molecular profiles of breast tumors linked to mutations in BRCA1, BRCA2 and ATM." (PMID 40259910, 2025). "Secondly, FANCC interacts with very important genes such as BRCA1, which is a well-established gene associated with breast neoplasms." (PMID 41296379, 2025). "Most BRCA1-mutated breast tumors, and a subset of BRCA2-mutated tumors, present as triple-negative breast cancer (TNBC), which is associated with a poor prognosis and high likelihood of recurrence." (PMID 38956205, 2024). "In our retrospective analyses of human breast tumors with BRCA1/2 or PALB2 mutations from patients, we observed a strong association between FLT1 activation in human tumor cells at pre-treatment and subsequent development of PARPi resistance." (PMID 38956205, 2024). "Intriguingly, luminal progenitors, the cells of origin of BRCA1-associated breast tumors, are particularly sensitive to telomere dysfunction." (PMID 38308367, 2024). "Microscopic examination of tumors with low ER expression revealed histologic features commonly present in breast tumors with basal-like molecular profiles and carcinomas harboring BRCA1 mutations." (PMID 36859337, 2023). "Decreased BRCA1 expression in sporadic breast tumors is associated with disease progression and poor prognosis." (PMID 37438760, 2023). "A homologous recombination deficiency typically associates with “BRCAness” of breast tumors due to mutational inactivation of the BRCA1 and BRCA2 tumor suppressor genes, making these tumors susceptible to poly-ADP ribose polymerase (PARP) inhibitors." (PMID 37906280, 2023). "The results of low HRDetect scores in our high-risk non-BRCA1/BRCA2 familial breast tumours are also supported by an independent method, our RNA-classifier, although a few tumours with low HRDetect scores were BRCA1- or BRCA2-like with this profile." (PMID 37316882, 2023). "This study clearly illustrates how in-depth proteomics coupled to analysis of protein functions and networks can yield a potential diagnostic and prognostic signature in BRCA1-deficient breast tumors." (PMID 37633929, 2023). "The regulation of AKT by BRCA1 in BRCA1-mutated breast tumors was suggested to participate in the effect of BRCA1 on glycolysis." (PMID 37109525, 2023). "Rag1KO mice that received WT CD4+ T cells were protected from Brca1-deficient breast tumor growth accompanied by the development of low-grade tumors compared with the Rag1KO + TslprKO CD4+ T cell control group (P = 0.0001)." (PMID 35657353, 2022). "We identified the combined inhibition of EZH2 and the proximal DNA damage response kinase ATM as a novel synthetic lethality-based therapy for the treatment of BRCA1-deficient breast tumors." (PMID 35715861, 2022). "Our study indicates that TAMs play an important role in influencing the response of BRCA1-deficient breast tumors to PARPi, supporting the need to assess the TIME in clinical trials." (PMID 35641483, 2022). "Given the highly M2-like nature of TAMs in BRCA1-deficient breast tumors, we next examined the interaction of macrophages and tumor cells in vitro in the presence or absence of olaparib." (PMID 35641483, 2022). "In contrast, approximately 20% of sporadic ER+ breast tumors, which had high BRCA1 expression in this study, were significantly associated with poor patient survival through reduced BRCA1 activity and uncontrolled ER signaling." (PMID 34996912, 2022).
breast tumors (continued). "Using a syngeneic genetically-engineered mouse model of breast tumor driven by Brca1 deficiency, we show that tumor-associated macrophages (TAMs) blunt PARPi efficacy both in vivo and in vitro." (PMID 35641483, 2022). "Breast tumors carrying BRCA1 mutants are linked to basal-like and triple-negative phenotypes, but those with BRCA2 mutations are generally of the luminal subtype." (PMID 35224098, 2022). "In agreement with the inability of mutant BRCA1 to suppress IGF1R transcription, primary breast tumors derived from BRCA1 mutation carrier patients expressed significantly higher levels of IGF1R than sporadic breast tumors." (PMID 35432218, 2022). "We found that olaparib-pretreated macrophages significantly delayed and slowed the progression of BRCA1-deficient breast tumors." (PMID 36223740, 2022). "Mutation of the BRCA1/2 gene is found not only in the breast but also in ovarian and pancreatic tumors, and this mutation occupied about 50% of breast tumor patients." (PMID 36547059, 2022). "Here, we demonstrate that BRCA1-deficient breast tumor cells strongly promote M2-like polarization of TAMs independent of PARPi treatment." (PMID 35641483, 2022). "Expression of BRCA2-001/Short was significantly more common in recurrent tumors and further enriched among breast tumors and BRCA1 mutation carriers." (PMID 36344544, 2022). "We propose an algorithm to predict the BRCA1 mutation of a patient according to the enhanced MRI of the breast tumor." (PMID 35402620, 2022). "All analyzed tumors were found to be ERα-negative, negative for or weakly expressing keratin 8, and keratin 14-positive, similar to breast tumors that tend to arise in carriers of BRCA1 pathological variants." (PMID 35393420, 2022). "Together, our data provide compelling evidence that combination of olaparib with systemic delivery of a STING agonist overcomes the resistance of STING-null BRCA1-deficient breast tumors to PARPi." (PMID 35641483, 2022). "Here the authors show that, by suppressing PARPi-triggered DNA damage and reducing dsDNA production in BRCA1-deficient breast tumor cells, tumor associated macrophages contribute to PARPi resistance, that can be overcome by STING agonism." (PMID 35641483, 2022). "BRCA1-associated murine breast tumors consist of CD44+/CD24− and CD133+ cells with bCSC-like features, showing a greater intrinsic colony-forming potential that can regenerate breast tumors in NOD/SCID mice." (PMID 35392236, 2022). "BRCA1-associated tumours are however biologically different from BRCA2-associated breast tumours, and should therefore be studied separately." (PMID 34929424, 2022). "In this study, we investigate transcriptomic data across multiple breast tumour datasets using differential variability analysis to identify genes that are associated with BRCA1 and BRCA2 pathogenic variant status and with different tumour subtypes." (PMID 34287743, 2021). "Clinically, BRCA1/2-mutated breast tumors tend to be classified as TNBC invasive ductal carcinoma with high nuclear grade while BRCA1/2-mutated ovarian tumors are predominantly classified as HGSOC." (PMID 33669749, 2021). "Increased variability in BRCA1-associated breast tumours was also observed in linear models of gene-specific CVs (25.0%, 95% CI 24.5–25.6) and MADs (32.4%, 95% CI 31.9–33.0)." (PMID 34287743, 2021). "It has been observed that breast tumours with BRCA1/2 mutations lack homologous repair recombination capabilities, making it difficult to repair DNA damage, causing cell apoptosis." (PMID 34830749, 2021). "RNA in situ analysis of EN1 supported a significant (p = 6.3 × 10−04) increase in expression variability in BRCA1-associated breast tumours." (PMID 34287743, 2021). "Our approach identified two genes (EN1 and IGF2BP3) that had increased variability in BRCA1-associated breast tumours." (PMID 34287743, 2021).
breast tumors (continued). "As a con-sequence, p21 is activated and BRCA1-deficient adipose-derived cells acquire senescent phenotype and secrete increased number of inflammatory cytokines, which promote breast tumor proliferation and invasion." (PMID 33540843, 2021). "For instance, an individual is at a higher risk of getting “breast tumor,” “ovarian tumor,” and “prostate tumor,” when inheriting the supposed “breast tumor genes,” certain mutations in BRCA1 and BRCA2." (PMID 33833800, 2021). "Though BRCA1 is not a direct transcriptional repressor of SLUG, a key EMT transcription factor, SLUG is aberrantly expressed in breast tumors with BRCA1 mutations." (PMID 35008272, 2021). "BRCA1-associated and basal-like breast tumours displayed a phenotype of greater gene expression variability, with no change in global RNA abundance." (PMID 34287743, 2021). "Using gene-specific standard deviations, BRCA1-associated breast tumours had a 22.8% (95% CI 22.3–23.2) increase in gene expression variability." (PMID 34287743, 2021). "Of these, two genes (EN1 and IGF2BP3) were significantly variable in both BRCA1-associated and basal-like breast tumours." (PMID 34287743, 2021). "As BRCA1-associated and basal-like breast tumours displayed greater transcriptome-wide expression variability, it was of interest to identify specific genes that had altered variability between tumour types." (PMID 34287743, 2021). "Our results provide a mechanism for the mutual exclusivity between oncogenic β-catenin activation and BRCA1/2 mutations observed in breast tumours." (PMID 34389725, 2021). "For example, more aggressive lymphocytic leukaemias are associated with greater gene expression variability, an observation that is consistent with the greater gene expression variability seen in BRCA1-associated and basal-like breast tumours." (PMID 34287743, 2021). "Loss of BRCA1 in mammary epithelial cells have been shown to affect stromal cells in the TME, which in turn enhance the metastatic potential of BRCA1-deficient breast tumors." (PMID 35008272, 2021). "BRCA1-associated breast tumours exhibited a 22.8% (95% CI 22.3–23.2) increase in transcriptome-wide gene expression variability compared to BRCAx tumours." (PMID 34287743, 2021). "Germline mutations in the tumor suppressor gene BRCA1 increase the risk of developing basal-like breast tumors with high metastasis and poor prognosis." (PMID 33540843, 2021). "In this study, we identified that BRCA1-associated and basal-like breast tumours displayed greater gene expression variability compared to non-BRCA1 and non-basal tumours, respectively." (PMID 34287743, 2021). "EN1 had greater expression variability in BRCA1-associated breast tumours, and this was captured in transcriptomic and RNA ISH analyses." (PMID 34287743, 2021). "After adjusting for multiple comparisons, 503 and 337 genes were found to be significantly differentially variable between BRCA1- and BRCAx-associated breast tumours in the Nagel and Larsen datasets, respectively." (PMID 34287743, 2021). "The objective of this review is to look at the role of BRCA1/2 mutations in the context of breast tumor microenvironment and plausible mechanisms by which it contributes to the aggressive behavior of the tumor cells." (PMID 33540843, 2021). "For radiation-associated secondary malignancies, a significant excess of long-segment-deletions relative to insertions was already described, which can typically be found in BRCA1 or BRCA2 germline-deficient breast tumors." (PMID 34885191, 2021). "Breast tumors arising from BRCA1 promoter hypermethylation and germline mutations acquired distinct morphology." (PMID 32856871, 2020). "Our analysis shows a correlation between the high level of ADAT2 and the BRCA1 deficiency among BRCA1 deficient breast tumor samples." (PMID 32290274, 2020). "Gene expression profiles from BRCA1-associated tumours were observed to be more similar to sporadic breast tumours than non-BRCA1/2 (BRCAx) hereditary breast tumours." (PMID 33081408, 2020).
breast tumors (continued). "In summary, we revealed that breast tumors with pathogenic germline BRCA1/2 variants show different genetic and clinical characteristics depending on the presence or absence of biallelic inactivation of these genes." (PMID 33067557, 2020). "Breast tumors from BRCA1/2 germline mutation carriers expressed M and LAR subtypes and none were immunomodulatory." (PMID 32164626, 2020). "A meta-analysis using four published datasets was conducted to identify differentially expressed genes between different BRCA1/2 pathogenic variant carriers and BRCAx/sporadic breast tumours." (PMID 33081408, 2020). "Conclusively, BRCAness is generally defined as breast tumors with sensitivity to DNA repair deficiency due to various mechanisms other than BRCA1/2 germline mutations." (PMID 33324554, 2020). "The presence of invading tumour lymphocytes, a feature of BRCA1-associated breast tumours, added complexity to gene expression profiles." (PMID 33081408, 2020). "Low BRCA1 expression in cells along with BRCA1 inactivation in breast tumors is associated with reduced expression of CCNL2, DBF4B, and TRIM45." (PMID 32290274, 2020). "We reviewed a total of nine studies that assessed differences in gene expression profiles between breast tumours from BRCA1 pathogenic variant carriers and non-BRCA1 pathogenic variant carriers." (PMID 33081408, 2020). "A previous study using DNA methylation data has also reached a comparable accuracy (~80%) in detecting breast tumors with BRCA1 mutations." (PMID 32483276, 2020). "Breast tumors with BRCA1 methylation also show the higher histological grade, like that of BRCA1-mutated tumors." (PMID 32903519, 2020). "HRDetect is a whole genome sequencing-based predictor that was developed to accurately detect BRCA1/2-deficient breast tumor samples." (PMID 30934991, 2019). "Mice models of BRCA1-deficient breast tumours have shown increased progesterone receptor expression in both the breast tumours and the adjacent benign tissue, and that mammary tumorigenesis can be prevented with progesterone inhibition." (PMID 30915162, 2019). "This is consistent with insertions/deletions found particularly at the hybrid containing transcription termination regions in breast tumors carrying germline BRCA1 mutations." (PMID 30813363, 2019). "BRCA1-associated breast tumors originate from luminal progenitor cells, yet they eventually become basal-like." (PMID 30995943, 2019). "Most BRCA1-associated breast tumors have a basal-like phenotype, with positive staining for the basal cell markers cytokeratin 5/6/14/17 and negative staining for the luminal cell markers estrogen receptor (ER) and progesterone receptor (PR)." (PMID 30995943, 2019). "BRCA1-associated breast tumors more often were invasive ductal carcinomas (99.0% vs. 91.4%, p=0.004), triple-negative (60.8% vs. 22.6%, p=<0.0001), and of higher tumor grade (grade 3: 94.9% vs. 63.2%, p=<0.0001) compared to tumors of non-carriers." (PMID 31528241, 2019). "To compare the point mutation profiles of BRCA1/2-mutated tumors with other breast tumors, we analyzed a published dataset of 560 breast tumors." (PMID 31182087, 2019). "Similar to BRCA1 mutation carriers, the hypermethylation of BRCA1 is associated with a BRCA1-deficient phenotype (i.e., BRCAness) and increased odds of developing sporadic breast tumors that are TNBC." (PMID 31652854, 2019). "We analyzed genomic data from breast tumors, with a focus on comparing tumors with BRCA1/BRCA2 gene mutations with common classes of sporadic breast tumors." (PMID 31182087, 2019). "Using mouse models and/or human breast tissues, it was shown that BRCA1-associated basal-like breast tumors originate from luminal progenitor cells." (PMID 30558184, 2018). "To explore this, we examined the expression of miRNAs differentially expressed in Brca1 deficient murine mammary glands with those miRNAs altered in 13 breast tumours of human BRCA1 mutation carriers (Published cohort)." (PMID 30323900, 2018).
breast tumors (continued). "MYC is a major oncogene in many cancers, including in BRCA1 breast tumours, where BRCA1 loss leads to overexpression of MYC contributing to tumourigenes." (PMID 30323900, 2018). "A breast tumor from a 33-year-old woman carrying a pathological germline BRCA1 mutation (c.302-1G>A) was obtained at surgery and subsequently engrafted in the mammary fat pad of female athymic mice." (PMID 29666142, 2018). "BRCA1-associated breast tumors, in particular, exhibit less DNA methylation compared with sporadic breast tumors." (PMID 30558184, 2018). "Contralateral breast tumours occurred in 151 (6%) patients: in 37 (18%) of 201 BRCA1 mutation carriers, 17 (12%) of 137 BRCA2 mutation carriers, and 97 (4%) of 2395 BRCA-negative patients." (PMID 29337092, 2018). "The single breast tumor that we identified with both BRCA1 mutation and CCNE1 amplification (PD13296a) had the highest number of rearrangements related to the RS1 signature (n = 1221) across all the tumors we analyzed." (PMID 30531861, 2018). "Previous investigations have shown that the majority of BRCA1-mutated breast tumors (over 80%) are categorized as triple-negative subtype." (PMID 28646826, 2018). "We identified differentially expressed miRNAs in Brca1 deficient mammary epitheial cells, human breast tumours and the developing mammary gland." (PMID 30323900, 2018). "In 2006, De Soto evaluated the sensitivity of multiple cell lines (non-cancerous mouse embryonic stem cells and hamster cells; human and mouse breast tumor cells) with BRCA1 or BRCA2 deficiency to three PARP1 inhibitors (NU1025, 3-aminobenzamide, and AG14361)." (PMID 29069872, 2017). "This luminal cell-specific R-loop accumulation is reminiscent of the lineage-specific cell of origin for BRCA1-associated breast tumours." (PMID 28649985, 2017). "In 7 cases (from families 1–6) we were able to retrieve for the analysis breast tumour samples, in which a putative mosaicism for a BRCA1/2 mutation should be detected at a higher frequency compared with other tissues." (PMID 28199346, 2017). "The BRCAness phenotype is related to sporadic TNBC, which shares clinical and histological characteristics with germline BRCA1-mutated breast tumours (young age, high grade and negativity for the ER, PgR and HER2)." (PMID 29259228, 2017). "This suggests that luminal progenitors are more likely the cells-of-origin for BRCA1 mutation-associated breast tumors, which was later confirmed in a transgenic mouse model study carried out by Molyneux and colleagues." (PMID 28148257, 2017). "Loss of BRCA1 expression and/or function has been shown to be significantly associated with highly aggressive metastatic breast tumor phenotype and a poor prognosis." (PMID 29156836, 2017). "In one previous report, BMI was significantly associated with methylation in the BRCA1 gene determined in DNA extracted from breast tumor tissue." (PMID 28594926, 2017). "Our computational framework starts by comparing familial breast tumors carrying either BRCA1 or BRCA2 mutations with sporadic cancer samples to generate a BRCAness characteristic profile." (PMID 29146938, 2017). "ID cisplatin treatment leads to a uniform reduction of the epithelial mammary cells and thereby prolongs breast tumor-free latency in a conditional BRCA1-associated mouse model." (PMID 28977823, 2017). "Analysis of the global gene methylation profiles of a cohort of 33 familial breast tumours revealed that FOXO3 promoter methylation is significantly associated with BRCA1 mutation." (PMID 27043660, 2016). "We found that breast tumors with inherited BRCA1 or BRCA2 mutations tend to have higher RIPSs than sporadic breast tumors." (PMID 27788678, 2016). "Methylation of the BRCA1 promoter in breast tumours is associated with a poor overall survival and disease-free survival and has been suggested as a biomarker to guide prognosis and targeted therapies." (PMID 27463681, 2016).